CASP9 (caspase 9)
Diseases named in the same sentence as CASP9 in open-access papers (continued):
Sharing a sentence is not in itself a finding about the gene and the disease.
kidney disease (6 papers, 2019 to 2024). "CASP9 is another gene that was prioritized as a kidney disease risk gene in proximal renal tubules through its higher tubular expression." (PMID 38124660, 2024). "We demonstrate the causal role of CASP9 in kidney disease development via improving mitophagy and lowering inflammation and apoptosis." (PMID 34739325, 2021). "Via the use of mouse genetic models, we demonstrated the causal role of CASP9 in AKI, fibrosis, and inflammation, rendering CASP9 a kidney disease risk gene." (PMID 34739325, 2021). "In summary, integrative genetic analysis, single-nuclear epigenome mapping, and CRISPR-Cas9 gene editing prioritized CASP9 as a kidney disease risk gene in kidney tubule cells where increased CASP9 expression was associated with renal disease risk." (PMID 34739325, 2021). "In summary, here, we prioritized CASP9 as an eGFR GWAS target gene and demonstrated the causal role of CASP9 in kidney disease development via improving mitophagy and lowering inflammation and apoptosis." (PMID 34739325, 2021). "Integration of GWAS and human kidney expression of quantitative trait analysis using Bayesian colocations, transcriptome-wide association studies, and summary-based Mendelian randomization studies prioritized caspase-9 (CASP9) as a kidney disease risk gene." (PMID 34739325, 2021). "Here, we demonstrate that CASP9 is a kidney disease risk gene prioritized by a variety of multiomics approaches." (PMID 34739325, 2021). "Kidney disease risk allele was associated with a roughly 30% higher CASP9 expression in human kidney tubule samples." (PMID 34739325, 2021). "Integrated omics analysis (GWAS, eQTL, snATAC, and mouse genetic models) identified caspase-9 as a kidney disease risk gene." (PMID 34739325, 2021). "In the prosess, the expression of Bax, Caspase-9/-3 was increased; the apoptosis of renal tubular epithelial cells was increased; renal tubular function was impaired so as to cause the kidney disease." (PMID 31269852, 2019). "Given that ferroptosis drives kidney disease, we tested the role of caspase-9 in ferroptosis in general." (PMID 38489367, 2024). "Follow-up mechanistic studies using in vitro and in vivo models demonstrated the role of CASP9 in kidney disease development by regulating not only apoptosis but also autophagy and mitophagy, thereby lowering inflammation and fibrosis." (PMID 34739325, 2021). "Interestingly pharmacological inhibition of CASP9 induces a dampened inflammation and lesser fibrosis, opening new horizons for kidney disease therapeutics." (PMID 38124660, 2024). "Our results could open new avenues for kidney disease therapeutics via the use of small molecular CASP9 inhibitors." (PMID 34739325, 2021). "The protective role of CASP9 in kidney disease development can be explained by two mechanisms." (PMID 34739325, 2021). "To examine the correlation between Casp9 expression and the degree fibrosis, we next evaluated collagen accumulation in the FA, UUO, UNx-STZ, and aging models of kidney disease." (PMID 34739325, 2021). "CASP9 expression in proximal tubules of FA and UUO mice and patients with CKD supports the key role of proximal tubule in kidney disease development." (PMID 34739325, 2021).
neurological disorders (6 papers, 2021 to 2025). "Our network analysis demonstrated that the most highly correlated targets between Mn-induced nervous system disease-related genes and Cc compound-related genes were CASP9, PTGS2, NOS1 and NOS2, which are primarily involved in oxidative stress and inflammation." (PMID 37904435, 2023). "Cc can treat Mn-induced nervous system diseases through targets such as CASP9, PTGS2, NOS1, and NOS2." (PMID 37904435, 2023).
bacterial infection (3 papers, 2009 to 2025). "A higher expression level of the intrinsic apoptotic initiator caspase-9, as well as the downstream effector caspase-3, was detected by Western blotting analysis of G6PD-deficient cells following bacterial infection." (PMID 24223971, 2013). "Accordingly, caspase-9 and caspase-3 were activated in a concentration-dependent manner by bacterial infection, whereas caspase-8 was not significantly affected." (PMID 19714221, 2009).
cardiovascular disease (3 papers, 2021 to 2024). "Studies have shown that hydroxychloroquine has a role in reducing the risk of cardiovascular disease events in patients with traditional risk factors, while chloroquine diphosphate promotes caspase-3 and caspase-9 activity and increases AMI cardiomyocyte apoptosis." (PMID 38764052, 2024). "Further research may identify common caspase-9-mediated pathways in autoimmune dysfunction and cardiovascular disease." (PMID 34305609, 2021). "Dysregulation of innate immunity is a driver of cardiovascular disease, implying that both pro-apoptotic and immune-regulatory functions of caspase-9 may be involved." (PMID 34305609, 2021).
colon (2 papers, 2015 to 2016). "Overexpression of CD44 has also been shown to potentiate resistance to etoposide by alteration of caspase 9, caspase 3, Bcl-xl, Bak, pRB, and phosphorylation of AKT in colon cancer." (PMID 26079799, 2015).
heart disease (2 papers, 2015 to 2021). "In mouse development, caspase-9 plays an essential nondeath role in muscle and cardiomyocyte differentiation and proliferation, supporting both apoptotic and nonapoptotic pathways of potential caspase-9 involvement in heart disease." (PMID 34305609, 2021).
lung (1 paper, 2019). "The treatment of cells with HPLC fraction 21 (25-35 kDa) of P.persicus venom resulted in high LDH release in normalfibroblast cells and high caspase-3 and caspase-9 activities in lung cancercells." (PMID 31555336, 2019).
myopathy (1 paper, 2016). A disease of the muscle in which the muscle fibers do not function properly. "A quite recent study evaluating apoptotic events in primary myoblast culture from GNE myopathy patients demonstrates enhanced active Caspase-3 and Caspase-9 in myoblast from patients." (PMID 26968811, 2016).
CASP9 also shares sentences with these, for which no sentence is quoted: Hypertension (7 papers); gastric tumor (3); Parkinson’s (3); renal cell carcinoma (3); acute promyelocytic leukemia (2); brain cancer (2); Burkitt lymphoma (2); cerebral infarct (2); clear cell renal cell carcinoma (2); diffuse large B-cell lymphoma (2); hearing loss (2); hemangioma (2); Huntington disease (2); inflammatory breast carcinoma (2); mycotoxicosis (2); rectal cancer (2); sarcoma (2); tuberculosis (2); acne vulgaris (1); acute kidney injury (1); acute myocardial infarction (1); adenocarcinoma (1); adenomyosis (1); alcoholic liver diseases (1); amyloid (1); bacteremia (1); bipolar disorder (1); bladder tumor (1); brain malignant glioma (1); breast angiosarcoma (1).
A further 68 diseases each share a sentence with CASP9 in 1 paper.